LINC01722 (long independently transcribed non-coding RNA 1722)
Gene: Long non-coding RNA gene on chromosome 20 (12,865,202 to 12,952,519, reverse strand). Ensembl gene ENSG00000233048.
Diseases named in the same sentence as LINC01722 in open-access papers:
LINC01722 is named in the same sentence as 1 disease in open-access papers, as found by Europe PMC text mining. Sharing a sentence is not in itself a finding about the gene and the disease. The quoted sentences say what the papers report.
ovarian carcinoma (1 paper, 2021). A malignant neoplasm originating from the surface ovarian epithelium. "We further observed that AC134312.1, AL133467.1, CHRM3-AS2, and LINC02207 were downregulated, whereas LINC01722 was upregulated in ovarian carcinoma compared with normal tissues." (PMID 33997040, 2021). "Except the absence of LINC01722 expression data, the expression of AL133467.1, CHRM3-AS2, and LINC01722 was downregulated in most detected ovarian carcinoma cell lines, which was consistent with our results from TCGA." (PMID 33997040, 2021). "The data showed that compared with adjacent normal cases, LINC01722 was upregulated, whereas AC134312.1, AL133467.1, CHRM3-AS2, and LINC02207 were downregulated in ovarian carcinoma." (PMID 33997040, 2021).